NLRP12 (NLR family pyrin domain containing 12)
Diseases named in the same sentence as NLRP12 in open-access papers (continued):
Sharing a sentence is not in itself a finding about the gene and the disease.
prostate carcinoma (6 papers, 2017 to 2023). A carcinoma that arises from epithelial cells of the prostate gland. "Increased expression of NLRP12 in prostate cancer suggest that NLRP12 may play an important role in activating NF-κB and IL-1β signaling, and its association with the pathogenesis and progression of prostate cancer." (PMID 28663562, 2017). "A previous study found that NLRP12 inflammasome induces inflammatory events during the development and progression of aggressive prostate cancer via regulating IL-1β and IL-18." (PMID 37658975, 2023). "They indicated that the NLRP12 inflammasome related to pyroptosis can upregulate Caspase-1 and downstream IL-1 β and IL-18 to promote the occurrence and progression of prostate cancer." (PMID 36702978, 2023). "We observed that constitutive expression of NLRP12 inflammasome sensor is significantly higher in prostate cancer as compared to adjacent benign tissues." (PMID 28663562, 2017). "To further understand the role of inflammasomes in prostate cancer, we analyzed the protein expression of inflammasome sensors NLRP3 and NLRP12, and its associated proteins ASC and pro-caspase-1." (PMID 28663562, 2017). "The expression of NLRP12 was significantly higher in prostate cancer compared to adjacent benign tissues." (PMID 28663562, 2017). "Recent studies also reported that an increased NLRP12 expression is associated with the progression of prostate cancer in the absence of increased levels of mature IL-1β or IL-18 by cancer cells." (PMID 34203890, 2021). "The dominant expression of inflammasome complex proteins (ASC and pro-caspase-1) in aggressive prostate cancer cell lines implicate the role of NLRP12 inflammasome provoking inflammatory events via regulating IL-1β and IL-18 in the development and progression of prostate cancer." (PMID 28663562, 2017). "Since inflammasome assembly is considered a master regulator of inflammation, determining the molecular function of NLRP12 as an upstream regulator of NF-κB, IL-1β, and IL-18 signaling will add to our understanding the molecular basis of inflammation induced prostate cancer." (PMID 28663562, 2017). "Furthermore, a recent study demonstrated that an increased NLRP12 expression is associated with the progression of prostate cancer in the absence of increased levels of mature IL-1β or IL-18 by cancer cells." (PMID 36980199, 2023). "Targeted inhibition of NLRP12 inflammasome may further help to appreciate the impact of inflammation on the biology of prostate tumors, and providing new directions investigating the role of inflammasomes in prostate cancer." (PMID 28663562, 2017). "It is likely that additional factors are required to activate and organize the formulation of NLRP12 inflammasome complex, similar to activation of AIM2 by the interferons (IFNs) in prostate cancer cell lines activating AIM2 inflammasome leading to interleukins IL-1β and IL-18 production." (PMID 28663562, 2017).
urticaria (6 papers, 2016 to 2024). A vascular reaction of the skin characterized by erythema and wheal formation due to localized increase of vascular permeability. "Namely, CU is, of course, recurrent, but in addition to chronic spontaneous and inducible urticaria, vasculitic urticaria, autoinflammatory urticaria (NLRP12-associated cold-induced autoinflammatory syndrome), etc. can be included in the recurrent urticaria class." (PMID 38883179, 2024).
autoimmune disease (5 papers, 2018 to 2023). A disorder resulting from loss of function or tissue destruction of an organ or multiple organs, arising from humoral or cellular immune responses of the individual to their own tissue constituents. "Certainly, the cross-interactions between pathogenic NLRP12 mutations in autoinflammatory and autoimmune disease certainly still require further study." (PMID 35123508, 2022). "Mutations in NLRP12 that cause increased secretion of IL-1β have been described in patients with FCAS, and supports a role for NLRP12 in the onset of autoimmune diseases." (PMID 31170158, 2019). "NLRP12 is a cytoplasmic sensor that can be categorized as a negative regulator of inflammation and is related to autoimmune diseases." (PMID 29721174, 2018). "Since sex differences exist, where females are more generally affected with autoimmune disease, to investigate the roles of NLRP12 in modulating inflammation in the B6/lpr model of autoimmunity, we monitored the disease progression in both male and female mice." (PMID 36969209, 2023). "In addition, Crohn’s disease, C3 glomerulopathy, juvenile idiopathic arthritis and other autoimmune diseases in some patients are also closely related to the functional imbalance of NLRP12 in acquired immunity." (PMID 35123508, 2022). "Thus, Nlrp12 may serve as an important immunomodulatory checkpoint in restricting autoimmune disease." (PMID 35313917, 2022).
Autoimmunity (5 papers, 2018 to 2025). The occurrence of an immune reaction against the organism's own cells or tissues. "Surprisingly, our data has shown that the deficiency of Nlrp12 ameliorates autoimmunity in our model in a sex-dependent manner." (PMID 36969209, 2023). "Together, these results suggest that Nlrp12 deficiency might target T cells to dampen autoimmunity in male B6/lpr mice." (PMID 36969209, 2023). "Interestingly, expression of Cxcl10 and Cxcl11, both of which have macrophage chemoattractant roles and are linked to autoimmunity and neuroinflammation, was most markedly upregulated in Nlrp12−/− retinas." (PMID 35313917, 2022). "NLRP12, a protein that regulates inflammation and plays a dual role in autoimmunity, is significantly altered in Nlrp12-/- B6/ lpr mice, especially in males." (PMID 40264032, 2025). "In the current work, we have investigated the role of NLRP12 in a Faslpr-mediated autoimmune mouse model of ALPS and SLE, B6/lpr." (PMID 36969209, 2023). "Although Nlrp12−/− mice have been reported to develop an attenuated form of classical EAE, we and others found Nlrp12−/− mice to be more susceptible to autoimmunity of the CNS." (PMID 35313917, 2022). "Collectively, current findings and controversies indicate that the exact immunoregulatory functions of Nlrp12 in T cell activation and T cell-mediated autoimmunity are poorly understood." (PMID 30150571, 2018). "The deficiency of Nlrp12 reduced the percentage of splenic CD3+ T cells and importantly, the generation of DN-T cells and TEM cells, which are known pathogenic T cell subsets in the autoimmunity." (PMID 36969209, 2023). "In this study, we used induced and spontaneous models of EAE, as well as in vitro T cell assays, to test the hypothesis that Nlrp12 inhibits Th1 response and prevents T-cell mediated autoimmunity." (PMID 30150571, 2018). "Contrary to our hypothesis, the deficiency of Nlrp12 in autoimmune-prone B6.Faslpr/lpr mice ameliorated autoimmunity in males but not females." (PMID 36969209, 2023). "Here, we sought to investigate the function of Nlrp12 using EAU, a T cell-mediated model of CNS autoimmunity similar to EAE." (PMID 35313917, 2022). "Additionally, inflammasomes play a vital role in the development and progression of autoimmunity, inflammation and metabolic disease, and many SNPs in inflammasome-associated genes, including NLRP1, NLRP3, NLRP12 and CARD8, are involved in and associated with patient susceptibility to T1DM." (PMID 34867336, 2021).
Crohn disease (5 papers, 2013 to 2024). A gastrointestinal disorder characterized by chronic inflammation involving all layers of the intestinal wall, noncaseating granulomas affecting the intestinal wall and regional lymph nodes, and transmural fibrosis. "Mutational analysis led us to identify the essential domain (residues 200–224) of NLRP12 that is interacting with the Crohn’s disease predisposing NOD2 protein." (PMID 30559449, 2018). "To date, only four alterations in the NLRP12 gene have been associated with Crohn's disease (CD)." (PMID 40225939, 2024). "Mutations in the genes encoding NLRP3 or NLRP12 lead to hereditary periodic fever syndromes, while mutations in CARD15 that encodes NOD2 are linked to Crohn’s disease or Blau’s syndrome." (PMID 24137163, 2013).
cryopyrin-associated periodic syndrome (5 papers, 2014 to 2024). Cryopyrin associated periodic syndrome (CAPS) defines a group of autoinflammatory diseases, characterized by recurrent episodes of systemic inflammatory attacks in the absence of infection or autoimmune disease. "It is noteworthy that periodic fever is a main symptom of cryopyrinopathies, a human inflammatory disorder that is associated with mutations in both NLRP3 and NLRP12 genes." (PMID 24453977, 2014).
periodic fever syndrome (5 papers, 2013 to 2021). Fevers of unknown etiology recurring over months or years. "Meanwhile, NLRP12 mutations cause hereditary periodic fever syndromes and systemic autoinflammatory diseases." (PMID 29721174, 2018). "NLRP12 is known to be associated with auto-inflammatory disease in humans, and mutations in the NBS and NOD domains can cause periodic fever syndromes." (PMID 23902802, 2013).
Sepsis (5 papers, 2018 to 2025). Sepsis is defined as life-threatening organ dysfunction caused by a dysregulated host response to infection. "At the opposite end of the spectrum of IEI genes induced by sepsis, we found that the most reduced genes are those encoding Nlrp12 (40x), Cxcr2 (35x) and Cr2 (12x)." (PMID 41229427, 2025). "In the GSE66099 control and sepsis groups, NCF2 (neutrophil cytosolic factor 2), NLRP12 (NLR family pyrin domain-containing 12), and NCR2 (natural cytotoxicity-triggering receptor 2) had degree 26, 26, and 34, respectively." (PMID 33667236, 2021).
familial cold autoinflammatory syndrome (4 papers, 2019 to 2025). Familial cold urticaria (FCAS) is the mildest form of cryopyrin-associated periodic syndrome (CAPS) and is characterized by recurrent episodes of urticaria-like skin rash triggered by exposure to cold associated with low-grade fever, general malaise, eye redness and arthralgia/myalgia. "A nonsynonymous mutation (c.C1054T: p.R352C) in the NLRP12 gene found in two patients suffering from familial cold autoinflammatory syndrome (FCAS) of different ancestries." (PMID 34905135, 2021). "Mutations in NLRP12 have been described in patients with familial cold autoinflammatory syndrome (FCAS), that causes symptoms similar to CAPS with fever, myalgia and elevated serum inflammatory markers." (PMID 31170158, 2019). "A total of 4 and 2 individuals were carriers for a causal variant in the ADAR and NLRP12 gene causative for Aicardi-Goutières syndrome (AGS) and familial cold autoinflammatory syndrome (FACS)." (PMID 34905135, 2021).
malaria (4 papers, 2014 to 2025). Malaria is a serious and sometimes fatal disease caused by a parasite that commonly infects a certain type of mosquito which feeds on humans. "Furthermore, we observed the presence of inflammasome complexes in monocytes from malaria patients containing either NLRP3 or NLRP12 pyroptosomes." (PMID 24453977, 2014). "Notably, we notice an in vivo assembly of NLRP3 and NLRP12 specks and ASC oligomerization in febrile malaria patients." (PMID 24453977, 2014). "We conclude that NLRP12/NLRP3-dependent activation of caspase-1 is likely to be a key event in mediating systemic production of IL-1β and hypersensitivity to secondary bacterial infection during malaria." (PMID 24453977, 2014). "However, in a human and murine study of infection using peripheral blood mononuclear cells, malaria induced the assembly of ASC, NLRP3 and NLRP12 inflammasomes jointly and promoted cleavage of procaspase-1, leading to IL-1β and hypersensitivity to bacterial superinfection." (PMID 38343435, 2023).
Salmonella Infections (4 papers, 2021 to 2025). Infections with bacteria of the genus SALMONELLA. "Previous studies showed that NLRP12 deficiency reduced bacterial burdens in salmonella infection but had no influence in influenza virus load." (PMID 34956178, 2021).
allergic disease (3 papers, 2012 to 2025). An immune response that occurs following re-exposure to an innocuous antigen, and that requires the presence of existing antibodies against that antigen. "Contact allergens, such as p-phenylenediamine (PPD) and 2,4-dinitrochlorobenzene (DNCB), increased the expression of Blimp-1 and IL-18, which are critical players in allergic diseases, but decrease NLRP12 expression in human keratinocytes, NCTC 2544 cells." (PMID 34299198, 2021). "Based on these findings we hypothesized that the Nlrp12−/− mouse would provide a suitable model to study the contribution of this gene in allergic diseases, including asthma." (PMID 22291998, 2012).
Arthritis (3 papers, 2019 to 2024). Inflammation of a joint. "Recent studies have shown that NLRP12 knockout (NLRP12-/-) in a mouse model of antigen-induced arthritis (AIA) with an increased Th17-associated inflammatory response develops more severe arthritis, and NLRP12 negatively regulates STAT3 phosphorylation of the IL-6 pathway." (PMID 35095918, 2021).
colorectal tumor (3 papers, 2022 to 2023). "Consistent with whole-body Nlrp12-KO mice, intestinal epithelial cell–specific Nlrp12-KO mice showed higher activation of β-catenin and expression of its downstream target cMyc and cyclin D1 in colorectal tumors." (PMID 37581937, 2023). "Consistently, the expression of NLRP12 was significantly reduced, while p-GSK3β and β-catenin were upregulated in mouse and human colorectal tumor tissues." (PMID 37581937, 2023). "Overall, this study establishes an intestinal epithelial cell–specific function of NLRP12 that potentially inhibits colorectal tumor progression and invasion." (PMID 37581937, 2023). "To understand whether these and other inflammatory pathways are dysregulated in Nlrp12–/– colorectal tumors, we measured the activation of NF-κB, ERK, JNK, STAT3, and AKT in tumors collected on day 80 after AOM/DSS treatment." (PMID 37581937, 2023). "NLRP12 is a key factor in maintaining intestinal homeostasis and preventing colorectal tumors." (PMID 35962453, 2022). "Interestingly, the expression of NLRP12 was markedly reduced in colorectal tumors compared with adjacent nontumor tissues of WT mice." (PMID 37581937, 2023). "Notably, although NF-κB and MAPK pathways were not dysregulated, there was increased STAT3 activation in colorectal tumors of Nlrp12–/– mice, which could be secondary to increased β-catenin." (PMID 37581937, 2023).
COVID-19 (3 papers, 2021 to 2023). A disease caused by infection with severe acute respiratory syndrome coronavirus 2. "More importantly, the direct cleavage of NLRP12 by 3CLpro could explain the hyper-inflammation observed in severe cases of COVID-19, potentially by pyroptosis-induced cytokine storm." (PMID 33372854, 2021). "Most relevant to COVID-19, NLRP12 is known to negatively regulate the release of pro-inflammatory cytokines and pyroptosis has recently be identified as one possible explanation for the cytokine storm observed in severe cases of COVID-19." (PMID 33372854, 2021). "The cleavage of IRF3 could explain the enigmatically blunted type-I IFN response that have been noted at early stages of SARS-CoV-2 infections, while the 3CLpro mediated cleavage of NLRP12 might explain the hyperinflammatory response observed at later stages in severe COVID-19 cases." (PMID 33372854, 2021). "Cleavage of IRF3 and critical modulators of inflammatory pathways (NLRP12 and TAB1) was proven by proteases nsp3 and nsp5 in SARS-CoV-2 infected 293T-ACE2 cells, which was involved in the pathophysiology of COVID-19." (PMID 37801439, 2023). "Direct cleavage of IRF3 by NSP3 could explain the blunted Type-I IFN response seen during SARS-CoV-2 infections while NSP5 mediated cleavage of NLRP12 and TAB1 point to a molecular mechanism for enhanced production of cytokines and inflammatory response observed in COVID-19 patients." (PMID 33372854, 2021).
familial cold-induced autoinflammatory syndrome (3 papers, 2011 to 2024). "Variants in SCN9A are associated with primary erythromelalgia, paroxysmal extreme pain disorder, or insensitivity to pain, and variants in NLRP12 are associated with familial cold-induced autoinflammatory syndromes." (PMID 39276275, 2024).
gastritis (3 papers, 2023 to 2024). Inflammation of the stomach. "A study in 2020 focusing on serum-derived exosomes from H. pylori-associated gastritis found that these exosomes upregulated NLRP12 in IECs to further inhibit the Notch signaling pathway." (PMID 37833958, 2023). "A study in 2023 on peptic ulcer disease found that the expression of NLRC4, NLRP12, IL-18 and IL-1β decreased significantly in patients of peptic ulcer disease compared with those of only H. pylori-associated gastritis." (PMID 37833958, 2023).
inflammatory bowel disease (3 papers, 2013 to 2025). A spectrum of small and large bowel inflammatory diseases of unknown etiology. "The lack of a role for NLRP12 in the disease processes assessed here is encouraging from the aspect of pharmacological inhibitors that target other inflammatory disorders, such as contact hypersensitivity or inflammatory bowel disease, where NLRP12 was found to play a role in a disease model." (PMID 23577168, 2013).
lupus (3 papers, 2023 to 2024). "NLRP12 deficiency enhances autoantibody formation and immune cell infiltration in a pristane-induced lupus-like mouse model." (PMID 36719379, 2023). "In this study, we evaluated the role of NLRP12 in the pathogenesis of lupus in 2 mouse models: pristane-induced lupus-like and Fas mutation–mediated lupus-prone models." (PMID 36719379, 2023). "Pristane-treated Nlrp12–/– mice exhibited augmented inflammation and immune responses; and substantial lymphoid hypertrophy was characterized in NLRP12-deficient lupus-prone mice." (PMID 36719379, 2023). "In summary, the deficiency of NLRP12 in lpr mice exacerbates disease progression in the typical lupus-prone model, causing a substantial shifting of plasma cells in the spleen and promoting the generation of more autoantibodies and leading to subsequent glomerular damage." (PMID 36719379, 2023). "Therefore, increased surface CD44 expression in DN T cells in Nlrp12–/–/lpr mice may correlate with greater immune activation and the potential mobilization of effector T cells at sites of inflammation in a lupus model driven by the lpr mutation." (PMID 36719379, 2023). "Peripheral blood mononuclear cells (PBMCs) derived from systemic lupus erythematosus (SLE) patients expressed lower levels of NLRP12, with an inverse correlation with IFNA expression and high disease activity." (PMID 36719379, 2023). "To validate the role of NLRP12 in a lupus model driven by genetic mutation, we generated autoimmune-prone mice by crossing B6.MRL-Faslpr/lpr/J mice with Nlrp12–/– mice." (PMID 36719379, 2023). "Collectively, we reveal a remarkable link between low NLRP12 expression and lupus progression, which suggests the impact of NLRP12 on homeostasis and immune resilience." (PMID 36719379, 2023). "Lupus patients with lower NLRP12 levels not only had increased levels of IFN-I, but also presented with deteriorated clinical parameters." (PMID 36719379, 2023). "To address the gap between serological markers and disease activity, we speculated that NLRP12 would be used as a serologic biomarker for “treat-to-target” in lupus patients because its expression level is increased in patients under adequate treatment." (PMID 36719379, 2023). "Importantly, the levels of NLRP12 gradually increased, with improved lupus disease activity after subsequent visits." (PMID 36719379, 2023). "Animal studies confirmed the finding that dysregulated/low NLRP12 expression causes an uncontrolled inflammatory reaction and IFN-I production, which not only accelerates disease progression, but also exacerbates the pathogenesis of lupus in animals." (PMID 36719379, 2023).